PKD1L1 (polycystin 1 like 1, transient receptor potential channel interacting)
Description:
Component of a calcium-permeant ion channel formed by PKD1L2 and PKD1L1 in primary cilia, where it controls cilium calcium concentration, without affecting cytoplasmic calcium concentration, and regulates sonic hedgehog/SHH signaling and GLI2 transcription. The PKD1L1:PKD2L1 channel complex is mechanosensitive only at high pressures and is highly temperature sensitive. Also involved in left/right axis specification downstream of nodal flow by forming a complex with PKD2 in cilia to facilitate flow detection in left/right patterning (By similarity). May function as a G protein-coupled receptor.
Synonyms: PRO19563; HTX8
Tractability: Antibody: UniProt predicts a signal peptide or a membrane-spanning region; its Gene Ontology location is reachable by antibodies, with medium confidence.
Gene: Protein-coding gene on chromosome 7 (47,740,202 to 47,948,466, reverse strand). Ensembl gene ENSG00000158683.
Subcellular location: Cell projection, cilium membrane
Gene Ontology:
Molecular function: protein binding; calcium channel activity
Biological process: cell-cell adhesion; detection of mechanical stimulus; detection of nodal flow; left/right axis specification; calcium ion transmembrane transport
Cellular component: calcium channel complex; ciliary membrane; non-motile cilium; cilium; membrane
Genetic constraint (gnomAD): Loss-of-function variants: 218 observed, 307.72 expected, observed/expected ratio (o/e) 0.71, 90% interval 0.63 to 0.79. The upper end of that interval is the gene's LOEUF score, 0.79, which puts it in group 3 of 6, group 1 being the genes least tolerant of losing a copy. Missense variants: 3,191 observed, 3,477.7 expected, observed/expected ratio (o/e) 0.92, 90% interval 0.89 to 0.94. Synonymous variants: 1,297 observed, 1,338.1 expected, observed/expected ratio (o/e) 0.97, 90% interval 0.93 to 1.01.
Homologues: Orthologues: chimpanzee PKD1L1 (98% identical), macaque PKD1L1 (91% identical), mouse Pkd1l1 (58% identical), dog PKD1L1 (50% identical), rat Pkd1l1 (45% identical), tropical clawed frog pkd1l1 (30% identical), Drosophila melanogaster Pkd2 (3% identical), Caenorhabditis elegans pkd-2 (3% identical). Paralogues in human: PKD1 (15% identical), PKD1L2 (11% identical), PKDREJ (11% identical), PKD1L3 (9% identical), LOXHD1 (7% identical), DENND5B (6% identical), DENND5A (6% identical), PKD2 (5% identical), PKD2L1 (4% identical), PKD2L2 (3% identical).
Diseases named in the same sentence as PKD1L1 in open-access papers:
PKD1L1 is named in the same sentence as 17 diseases in open-access papers, as found by Europe PMC text mining. Sharing a sentence is not in itself a finding about the gene and the disease. The quoted sentences say what the papers report.
congenital heart disease (3 papers, 2020 to 2023). A heart disease that is present at birth. "Moreover, patients with mutations in PKD1L1 or in PKD2 present laterality phenotypes such as situs inversus, heterotaxia and congenital heart disease." (PMID 37477290, 2023).
congenital heart malformation (1 paper, 2022). A disease that has its basis in the disruption of heart development. "Biallelic variants in PKD1L1 have been previously reported in individuals with laterality defects and congenital heart malformations." (PMID 35547246, 2022).
Duodenal stenosis (1 paper, 2022). The narrowing or partial blockage of a portion of the duodenum. "In a male individual (HET25_501) with heterotaxy comprising left sided inferior vena cava, joining right atrium, midline positioned liver, accessory spleen, and membranous duodenal stenosis, a compound heterozygous VUS in PKD1L1 coding for Polycystin 1-Like 1 was found." (PMID 35474353, 2022).
fetal hydrops (1 paper, 2024). "In 2021, Correa and colleagues reported two fetuses in the same family with ultrarare compound heterozygous deleterious variants in PKD1L1 exhibiting fetal hydrops." (PMID 38247840, 2024). "In Family 2 (PUV146), we detected compound heterozygous PKD1L1 variants (p.Gln2183His and p.Asn288Thrfs*3) in patient PUV146_501, who presented with lethal bilateral hydrothorax and hydrops fetalis." (PMID 38247840, 2024). "In Family 1 (CHT3), we detected compound heterozygous PKD1L1 missense variants (p.Gly515Arg and p.Val1282Glu) in patient CHT3_501, who presented with left-sided CCT and hydrops fetalis." (PMID 38247840, 2024).
hydrops (1 paper, 2024). "With no other cause identified, Correa and colleagues assumed a direct involvement of the PKD1L1 variants in fetal hydrops formation." (PMID 38247840, 2024). "In 2021, Correa and colleagues reported ultrarare compound heterozygous variants in PKD1L1 exhibiting in two consecutive fetuses with severe hydrops, implicating a direct role of PKD1L1 in fetal hydrops formation." (PMID 38247840, 2024).
Pleural effusion (1 paper, 2024). The presence of an excessive amount of fluid in the pleural cavity. "The presence of pleural effusion in Pkd1l1−/− embryos is of great interest due to the identification of human PKD1L1 variants associated with pleural effusion in this study." (PMID 38247840, 2024). "Further analysis of Pkd1l1 mutant mouse embryos revealed about 20% of Pkd1l1−/− embryos display general edema and pleural effusion at 14.5 dpc." (PMID 38247840, 2024). "Compound heterozygous or homozygous LoF PKD1L1 variants can result in pleural effusion with or without changes to situs." (PMID 38247840, 2024). "However, in conjunction with our findings on the abnormal lymphatic vessels and external edema, the observation of pleural effusion indicates that Pkd1l1 is an important mediator of lymphatic system development in both mice and humans, suggesting a conserved function across these two species." (PMID 38247840, 2024).
polycystic kidney disease (1 paper, 2024). A usually autosomal dominant and less frequently autosomal recessive genetic disorder characterized by the presence of numerous cysts in the kidneys leading to end-stage renal failure. "In the PKD1L1 protein structure variant, c.1543G>A(p.Gly515Arg) is located in the first functional polycystic kidney disease domain (PKD) of the protein, and variant c.3845T>A(p.Val1282Glu) is located in the functional receptor for egg jelly domain (REJ) of the protein." (PMID 38247840, 2024). "PKD1L1 largely consists of a long N-term ectodomain and a C-term 11-transmembrane polycystic kidney disease (PKD) channel domain." (PMID 38247840, 2024).
visceral heterotaxy (1 paper, 2023). A rare, genetic disorder in which symptoms are generally secondary to the abnormal location of the organs within the thoracic, abdominal, or peritoneal cavities. "The homozygous variant in the PKD1L1 gene is responsible for visceral heterotaxy-8 (OMIM#617205)." (PMID 37260775, 2023).
PKD1L1 also shares sentences with these, for which no sentence is quoted: situs inversus (2 papers); Alagille syndrome (1); biliary atresia (1); Chylothorax (1); liver disease (1); Neonatal respiratory distress (1); polycystic kidney and hepatic disease 1 (1); polycystic kidney disease 2 (1); Situs inversus totalis (1).